VLDLR (very low density lipoprotein receptor)
Diseases named in the same sentence as VLDLR in open-access papers (continued):
Sharing a sentence is not in itself a finding about the gene and the disease.
type 2 diabetes (4 papers, 2010 to 2025). "Notably, it has been shown that EAT overexpresses lipoprotein receptors, such as low-density lipoprotein receptor 1 and very low-density lipoprotein receptor, playing a role in the changes in lipid metabolism normally associated with type 2 diabetes." (PMID 36158806, 2022).
Cognitive impairment (3 papers, 2016 to 2020). Abnormal cognition is characterized by deficits in thinking, reasoning, or remembering. "In addition, single nucleotide polymorphisms (SNPs) in the APOER2, VLDLR, and DAB1 genes are associated with cognitive impairments in patients with schizophrenia." (PMID 32982694, 2020).
dyslipidemia (3 papers, 2017 to 2024). "Recent investigations also advance the notion that alcohol-induced injury to the pancreas could yield an amplified activation of the very low density lipoprotein receptor (VLDLR), consequentially inciting intracellular lipid accumulation and the ensuing development of dyslipidemia within PSCs." (PMID 38255213, 2024). "This metabolic shift is mediated by epigenetic mechanisms that up-regulate genes involved in hepatic lipogenesis such as PPARγ, very low-density lipoprotein receptor (VLDLR), and CD36, contributing to the onset of steatotic liver disease and intensifying the effects of metabolic syndrome." (PMID 39796579, 2024).
schizophrenia (3 papers, 2019 to 2023). A major psychotic disorder characterized by abnormalities in the perception or expression of reality. "Examination of peripheral blood lymphocytes in patients with schizophrenia expressed low activity of very low-density lipoprotein receptor (VLDLR) for reelin in drug-naive, unmedicated patients, and unchanged activity of apolipoprotein E receptor type 2 (ApoER2)." (PMID 38137152, 2023).
Clear-Cell Renal Cell Carcinoma (2 papers, 2012 to 2022). "A previous study showed that expression of VLDLR was significantly increased in human clear-cell renal cell carcinoma (RCC) biopsies, which are characterized histologically by accumulation of cholesterol." (PMID 36568166, 2022).
Glucose intolerance (2 papers, 2017 to 2024). Glucose intolerance (GI) can be defined as dysglycemia that comprises both prediabetes and diabetes. "Here we show that elevated VLDLR expression in ATMs promotes adipose tissue inflammation and glucose intolerance in obese mice." (PMID 29057873, 2017).
hyperlipidaemia (2 papers, 2019 to 2022). "Considering that VLDLR is important in postprandial chylomicron and VLDL clearance, the upregulation of VLDLR is thought to lower serum lipids, which is opposite of the hyperlipidemia phenotype seen in both offspring-pLPS and TLR2-deficient offspring-pLPS." (PMID 31507457, 2019).
hyperplasia (2 papers, 2022 to 2023). An abnormal increase in the number of cells in an organ or a tissue with consequent enlargement. "In addition, binding to low-density lipoprotein receptor-related protein 1 (LRP1), apolipoprotein E receptor-2 (ApoER2), very-low-density lipoprotein receptor (VLDLR), and other receptors promotes vascular endothelial hyperplasia and increases lipoprotein levels." (PMID 36980904, 2023). "Low-density lipoprotein receptor-related protein 1 (LRP1), apolipoprotein E receptor-2 (ApoER2), very-low-density lipoprotein receptor (VLDL-R), and other receptors can promote vascular endothelial hyperplasia and increase lipoprotein concentrations." (PMID 36230934, 2022).
lung carcinoma (2 papers, 2024 to 2025). "On the other hand, hsa‐miR‐99a‐5p promotes cisplatin sensitivity and induces apoptosis by suppressing Very Low‐Density Lipoprotein Receptor (VLDLR) expression in lung cancer." (PMID 40444136, 2025). "Intriguingly, it was reported that miR-99a-5p overexpression enhances sensitivity to cisplatin (DDP) and cell apoptosis by suppressing VLDLR expression in lung cancer cells, and miR-99a inhibits two novel oncogenic proteins E2F2 and EMR2 and represses stemness in lung cancer." (PMID 39628814, 2024).
pancreatic cancer (2 papers, 2016 to 2020). "A similar inhibitory effect of miR-135a was revealed in pancreatic cancer by its targeting of Bmi-128 and in gallbladder cancer by its targeting of very low density lipoprotein receptor (VLDLR); the p38 MAPK pathway is the downstream signaling pathway of miR-135a-VLDLR36." (PMID 32944391, 2020).
viral infection (2 papers, 2019 to 2024). "We further mutated the residues at the interface of SFV E1-DIII, rescued the mutated virus, and assessed its impact on viral infection in BHK-21, HEK293T, and K562 cells that express the wild-type VLDLR." (PMID 39705215, 2024). "Post PCV2 infection, we identified 199 differentially expressed lncRNAs, which appear to modify genes associated with viral infection, such as SOD2, TNFAIP3, ARG1, SERPINB2, VLDLR, HSPA5, and LCN2." (PMID 30863688, 2019).
acute myocardial infarction (1 paper, 2012). Necrosis of the myocardium, as a result of interruption of the blood supply to the area. "We also found VLDLR protein overexpressed in a porcine model of acute myocardial infarction and in human ischemic hearts." (PMID 22873206, 2012).
age-related macular degeneration (1 paper, 2016). Age-related loss of vision in the central portion of the retina (macula), secondary to retinal degeneration. "In the retinas of VLDLR knockout mice spontaneous retinal-chorodoidal neovascularizations form, having an appearance similar to choroidal and retinal neovascularizations (CNV and RNV) in neovascular age-related macular degeneration (AMD) or retinal angiomatous proliferation (RAP)." (PMID 27711217, 2016).
alcohol (1 paper, 2020). "In fact, Wang and collaborators found that Nrf2-signalling positively modulated the expression of hepatic very low-density lipoproteins receptor (VLDLR), which contributes to the development of alcohol-induced liver injury." (PMID 33053665, 2020).
aortic atherosclerosis (1 paper, 2018). A atherosclerosis that involves the aorta.
breast tumors (1 paper, 2022). "Taken together, these results suggested that VLDLR may act as an important protein to promote cancer progression in human breast tumors, especially in TNBC." (PMID 36568166, 2022).
chronic hepatitis C (1 paper, 2016). "Therefore, it might be feasible to speculate that expression of VLDLR and CLDN6/9 enables HCV to be internalized into various non-hepatic tissues, leading to development of the extrahepatic manifestations that sometimes occur in chronic hepatitis C patients." (PMID 27152966, 2016).
dysplastic nevi (1 paper, 2017). "In dysplastic nevi, VLDLR stained weakly positive in 78% of the cases (11/ 14), and in 28% of the cases (5/ 18) of non-dysplastic nevi." (PMID 28255385, 2017).
encephalitis (1 paper, 2025). An acute inflammatory process affecting the brain parenchyma. "Imperial 181 does not bind VLDLR, ApoER2, or PCDH10, and has been shown to replicate poorly in the brain of infected mice, suggesting an impaired ability to infect neurons and cause encephalitis compared to virulent WEEV strains." (PMID 40187345, 2025).
Epileptic seizures (1 paper, 2015). "Epileptic seizures occur in a proportion of humans with VLDLR-associated cerebellar hypoplasia, and also with DWM and related malformations." (PMID 25668516, 2015).
heart failure (1 paper, 2024). Inability of the heart to pump blood at an adequate rate to meet tissue metabolic requirements. "In WT mouse models, VLDLR exacerbates the cardiomyocyte lipid burden and hastens the progression of heart failure." (PMID 39139638, 2024).
herpesvirus infection (1 paper, 2012). "• The meaning of down-regulation of VLDLR in ILTV vaccine infection in addition to in other herpesvirus infection, is unknown." (PMID 22530940, 2012).
ischemia (1 paper, 2019). A hypoperfusion of the BLOOD through an organ or tissue caused by a PATHOLOGIC CONSTRICTION or obstruction of its BLOOD VESSELS, or an absence of BLOOD CIRCULATION. "This hypothesis is supported by the demonstration that very low density lipoprotein receptor (VLDLR) depletion reduces the accumulation of ischemia-induced lipids in mouse hearts." (PMID 31330812, 2019).
ischemic cardiomyopathy (1 paper, 2012). Ischemic cardiomyopathy is a cardiomyopathy in which a weakness in the muscle of the heart due to inadequate oxygen delivery to the myocardium with coronary artery disease being the most common cause. "It has been previously suggested that cyclosporine, an immunosuppressant used for the treatment of transplant recipients, inhibits VLDLR mRNA expression in the myocardium of ischemic cardiomyopathy patients." (PMID 22873206, 2012).
liver fibrosis (1 paper, 2024). "In summary, the expression of VLDLR is considerably upregulated in severe liver fibrosis." (PMID 38195587, 2024).
metastatic tumors (1 paper, 2016). "Metabolic advantage is a feature of metastatic tumors and might be mediated by overexpression of VLDLR, USP32, and PITPINC1." (PMID 27136531, 2016).
nevus (1 paper, 2017). Nevus (or naevus, plural nevi or naevi, from nævus, Latin for "birthmark") is the medical term for sharply circumscribed[1] and chronic lesions of the skin or mucosa. "We investigated the reelin presence and its receptors, VLDLR and ApoER2, in melanocytic nevi considering the neural crest origin of the nevus cells and their migration into skin during embrionary period." (PMID 28255385, 2017).
osteoporosis (1 paper, 2024). A condition of reduced bone mass, with decreased cortical thickness and a decrease in the number and size of the trabeculae of cancellous bone (but normal chemical composition), resulting in increased fracture incidence. "Our study systematically identified seven candidate hub genes (PDP1, ALS2CL, VLDLR, PLEKHA6, PPP1CB, MOSPD2, and METTL9) through a combination of various bioinformatics analyses and machine learning algorithms, and provided a nomogram for diagnosing sarcopenia associated with osteoporosis." (PMID 38831425, 2024). "We identified 7 candidate hub genes (PDP1, ALS2CL, VLDLR, PLEKHA6, PPP1CB, MOSPD2, METTL9) and constructed column line plots for osteoporosis combined with sarcopenia." (PMID 38831425, 2024). "A notable finding is the identification of 7 key candidate genes (PDP1, ALS2CL, VLDLR, PLEKHA6, PPP1CB, MOSPD2, and METTL9), and the development of a nomogram for diagnosing osteoporosis in sarcopenia patients." (PMID 38831425, 2024).
osteosarcoma (1 paper, 2020). A usually aggressive malignant bone-forming mesenchymal neoplasm, predominantly affecting adolescents and young adults. "In agreement with this hypothesis, several osteosarcoma cell lines present a high expression of ACAT, HIF1A, and VLDLR." (PMID 33178572, 2020).
paraganglioma (1 paper, 2021). A benign or malignant neoplasm arising from paraganglia located along the sympathetic or parasympathetic nerves. "The cluster analysis showed that SDH-deficient GISTs and SDHB-mutant pheochromocytoma/paraganglioma shared the expression of hypoxia genes that is particularly evident for FOXO3, VLDLR, and ENO2." (PMID 33806389, 2021).
polymicrogyria (1 paper, 2024). A developmental brain abnormality characterized by an excessive amount of small convolutions on the surface of the brain and cognitive dysfunction. "However, in the case of polymicrogyria-associated variants, the canonical RELN signaling cascade involving ApoER2/VLDLR appears to be unaffected based on the well-organized rosettes formed." (PMID 38980724, 2024).
tendinopathy (1 paper, 2022). "Linkage of VLDLR variants with tendinopathy has not been established." (PMID 35866615, 2022).
triple-negative breast carcinoma (1 paper, 2022). An invasive breast carcinoma which is negative for expression of estrogen receptor (ER), progesterone receptor (PR), and human epidermal growth factor receptor 2 (HER2). "Analysis with the GENT2 database revealed that VLDLR mRNA expression was significantly higher in triple-negative breast cancer than in other subtypes." (PMID 36568166, 2022). "Furthermore, by analyzing VLDLR expression in the GENT2 database, we observed that the VLDLR mRNA expression levels were significantly increased in triple-negative breast cancer (TNBC) compared to other subtypes." (PMID 36568166, 2022).
infection (18 papers, 2012 to 2026). The state of being infected such as from the introduction of a foreign agent such as serum, vaccine, antigenic substance or organism. "Albeit, the ingenuity connectome showed that lipids and cholesterol were found to be prominently linked with receptors like HRH1/VLDLR and altered function of these receptors has a significant role in infection-related neuroinflammation." (PMID 37876925, 2023). "Ectopic expression of ApoER2 ligand binding domains (LBD) in K562 cells devoid of either VLDLR or ApoER2 supported the infection of SFV, EEEV, and SINV, which was demonstrated to be inhibited by the addition of a soluble decoy receptor." (PMID 40733635, 2025). "High-resolution maps allowed us to unambiguously build LA1 and LA2, with LA1 positioned deepest in the cleft (site 1), consistent with McMillan RVPs infection of K562 cells expressing VLDLR LA1 or LA2." (PMID 40187345, 2025). "In entry-blocking assays with soluble receptor–Fc fusion proteins using K562 cells ectopically expressing PCDH10, VLDLRLBD–Fc blocked infection by all five group A strains, suggesting that these strains bind VLDLR in a manner that competes with PCDH10 binding." (PMID 39048821, 2024). "Small interfering RNA (siRNA) experiments revealed that VLDLR is critical for an efficient infection by rhinovirus 1B." (PMID 27795362, 2017). "Interestingly, the original mutations concomitantly increased HS interactions and reduced infection promoted by VLDLR and PCDH10 protein receptors, while the second site mutations improved infectivity mediated by VLDLR." (PMID 41662398, 2026). "We tested whether the group A WEEV strains could have engaged VLDLR and ApoER2 during infection of human, avian, equine and mosquito hosts." (PMID 39048821, 2024). "Moreover, the ingenuity pathway analysis revealed protein molecules such as VLDLR, MBP and APP that are associated with altered profile of cholesterol, fatty acids and triglycerides with infection-related CNS disorders." (PMID 37876925, 2023). "Additionally, we found that PCDH10EC1–Fc could block McMillan RVP infection of K562 cells expressing VLDLR or ApoER2 and infection of Vero E6 cells by replication-competent WEEV McMillan, confirming that PCDH10EC1–Fc can block access to multiple receptors that redundantly support WEEV infection." (PMID 39048821, 2024). "The site 1 R224K substitution when introduced into McMillan RVPs did not prevent infection of K562 cells expressing VLDLR, suggesting that lysine and arginine are interchangeable at this position." (PMID 40187345, 2025). "Our finding that VLDLRLBD–Fc could block WEEV McMillan RVP infection of K562 cells stably expressing PCDH10 suggests that group A strains recognize PCDH10 and VLDLR through an overlapping surface on their E2–E1 spike proteins." (PMID 39048821, 2024).
infection (continued). "Although VLDLR is expressed in multiple tissues, it has been observed that the absence of VLDLR or presence of antibodies against VLDLR do not completely block the infection of SFV in Vero, U2OS, A549, Huh7, and other cells." (PMID 38245515, 2024). "To confirm that PCDH10, VLDLR and ApoER2 can support infection by group A WEEV strains, we rescued replication-competent WEEV Fleming and McMillan from molecular clones, and found they replicated faster and to higher levels in K562 cells expressing PCDH10, VLDLR or ApoER2 than in control cells." (PMID 39048821, 2024). "However, since minor group RVs interact with entry receptors (VLDLR) at a site distant from the canyon known as the VP1 5-fold axis of symmetry, RMN binding is less likely to sterically hinder VLDLR engagement and therefore display reduced inhibition of infection in vitro." (PMID 40699732, 2025). "Only three out of the eight VLDLR LA repeats (LA4, LA7, and LA8) could not support infection by any of the RVPs we tested, suggesting that these particular LA repeats lack critical determinants required for interaction with alphavirus spike proteins." (PMID 39095394, 2024). "The VLDLR-negative K562 cell line supported infection of both A774 and SFV4(A774st) resulting in >100-fold higher virus titers in the culture medium as compared to SFV4 at the d2 time point post infection." (PMID 39715740, 2024). "Nonetheless, infection of CHIKV, VEEV, or WEEV was not supported by VLDLR or ApoER2." (PMID 36647825, 2023).